FFAR3 (free fatty acid receptor 3)
Description:
G protein-coupled receptor that is activated by a major product of dietary fiber digestion, the short chain fatty acids (SCFAs), and that plays a role in the regulation of whole-body energy homeostasis and in intestinal immunity. In omnivorous mammals, the short chain fatty acids acetate, propionate and butyrate are produced primarily by the gut microbiome that metabolizes dietary fibers. SCFAs serve as a source of energy but also act as signaling molecules. That G protein-coupled receptor is probably coupled to the pertussis toxin-sensitive, G(i/o)-alpha family of G proteins. Its activation results in the formation of inositol 1,4,5-trisphosphate, the mobilization of intracellular calcium, the phosphorylation of the MAPK3/ERK1 and MAPK1/ERK2 kinases and the inhibition of intracellular cAMP accumulation. Activated by SCFAs and by beta-hydroxybutyrate, a ketone body produced by the liver upon starvation, it inhibits N-type calcium channels and modulates the activity of sympathetic neurons through a signaling cascade involving the beta and gamma subunits of its coupled G protein, phospholipase C and MAP kinases. Thereby, it may regulate energy expenditure through the control of the sympathetic nervous system that controls for instance heart rate. Upon activation by SCFAs accumulating in the intestine, it may also signal to the brain via neural circuits which in turn would regulate intestinal gluconeogenesis. May also control the production of hormones involved in whole-body energy homeostasis. May for instance, regulate blood pressure through renin secretion. May also regulate secretion of the PYY peptide by enteroendocrine cells and control gut motility, intestinal transit rate, and the harvesting of energy from SCFAs produced by gut microbiota. May also indirectly regulate the production of LEP/Leptin, a hormone acting on the CNS to inhibit food intake, in response to the presence of short-chain fatty acids in the intestine. Finally, may also play a role in glucose homeostasis. Besides its role in energy homeostasis, may play a role in intestinal immunity. May mediate the activation of the inflammatory and immune response by SCFAs in the gut, regulating the rapid production of chemokines and cytokines by intestinal epithelial cells. Among SCFAs, the fatty acids containing less than 6 carbons, the most potent activators are probably propionate, butyrate and pentanoate while acetate is a poor activator.
Synonyms: GPR41; FFA3R
Tractability: Small molecule: a structure with a bound ligand is known; a high-quality ligand is known; it belongs to a druggable protein family. Antibody: UniProt places it where antibodies can reach, with high confidence; its Gene Ontology location is reachable by antibodies, with high confidence; UniProt predicts a signal peptide or a membrane-spanning region. PROTAC: a small molecule that binds it is known.
Target class: Family A G protein-coupled receptor; Small molecule receptor (family A GPCR); Membrane receptor; Free fatty acid receptor; Lipid-like ligand receptor (family A GPCR)
Gene: Protein-coding gene on chromosome 19 (35,358,348 to 35,360,489, forward strand). Ensembl gene ENSG00000185897.
Subcellular location: Cell membrane
Pathways (Reactome):
Signal Transduction: Free fatty acid receptors; G alpha (q) signalling events
Gene Ontology:
Molecular function: G protein-coupled receptor activity; protein binding
Biological process: adenylate cyclase-inhibiting G protein-coupled receptor signaling pathway; cellular response to fatty acid; G protein-coupled receptor signaling pathway; mucosal immune response; negative regulation of blood pressure; positive regulation of acute inflammatory response to non-antigenic stimulus; positive regulation of chemokine production; positive regulation of cytokine production involved in immune response; regulation of hormone biosynthetic process; regulation of insulin receptor signaling pathway; regulation of norepinephrine secretion; regulation of peptide hormone secretion
Cellular component: plasma membrane; membrane
Genetic constraint (gnomAD): Loss-of-function variants: 0 observed, 0.23 expected, observed/expected ratio (o/e) 0, 90% interval 0 to 1.87. That is too few expected variants to judge how well the gene tolerates losing a copy. Missense variants: 133 observed, 313.65 expected, observed/expected ratio (o/e) 0.42, 90% interval 0.37 to 0.49. Synonymous variants: 65 observed, 131.74 expected, observed/expected ratio (o/e) 0.49, 90% interval 0.4 to 0.61.
Homologues: Orthologues: chimpanzee FFAR3 (99% identical), mouse Ffar3 (70% identical), rat Ffar3 (69% identical), zebrafish si:ch73-90p23.1 (38% identical), zebrafish si:dkey-211g8.6 (37% identical), zebrafish si:dkey-211g8.7 (33% identical). Paralogues in human: GPR42 (98% identical), FFAR2 (36% identical), FFAR1 (27% identical), P2RY2 (22% identical), HCAR3 (21% identical), P2RY1 (21% identical), HCAR2 (21% identical), P2RY6 (21% identical), P2RY4 (20% identical), SUCNR1 (19% identical), GPR31 (19% identical), HCAR1 (19% identical), and 3 more.
Diseases named in the same sentence as FFAR3 in open-access papers:
FFAR3 is named in the same sentence as 95 diseases in open-access papers, as found by Europe PMC text mining. Sharing a sentence is not in itself a finding about the gene and the disease. The quoted sentences say what the papers report.
Obesity (56 papers, 2012 to 2025). Accumulation of substantial excess body fat. "FFAR2 and FFAR3 have also been associated with inflammation and metabolic diseases such as diabetes and obesity." (PMID 36404915, 2022). "Regarding obesity, the reduced abundance of Faecalibacterium prausnitzii in patients was correlated with hypomethylation of the free fatty acid receptor 3 (FFAR3) gene." (PMID 40842134, 2025). "Our results demonstrate that the HFD induces a significant decrease in FFAR3 expression, a finding consistent with previous studies that report alterations in sensitivity to SCFAs in states of obesity." (PMID 41149616, 2025). "In the subjects with obesity, before surgery, the jejunal protein expression of FFAR3 was significantly higher in the jejunum compared to the duodenum (p = 0.001)." (PMID 38910871, 2024). "In the normal weight subjects, the FFAR3 expression was higher in the duodenum while the opposite was seen in subjects with obesity." (PMID 38910871, 2024). "Several groups have also examined phenotypes related to body weight and/or obesity in FFAR3-KO mice." (PMID 36678142, 2023). "FFAR2 (GPR43) and FFAR3 (GPR41) are selectively activated by SCFAs, thus activating metabolic pathways in the setting of obesity and obesity-related diseases." (PMID 36678142, 2023). "In the light of a scenario where aging, obesity, and T2DM appear to be closely linked to neurodegeneration, these data postulate FFAR3 as a potential novel target for AD." (PMID 36362376, 2022). "Previous studies have demonstrated the positive effects of propionate and other SCFAs in reducing food intake; therefore, we investigated the contribution of vagal FFAR3 to SCFA-induced decrease in food intake in our WD-induced obesity model." (PMID 34626852, 2021). "These evidence shows FFAR3 signaling similar to FFAR2 is a promising therapeutic target for treating gut related disorders such as obesity, T2D, colitis and diarrhea, by honing gut-hormonal synthesis and balancing the microbiome-gut-brain axis." (PMID 32521775, 2020). "Further studies, however, are needed to characterize any potential involvement of the short chain fatty acid receptor FFAR3 in contributing to the phenomenon we uncover here, namely of a novel, obesity-induced depression phenotype." (PMID 31076569, 2019). "Overall, we showed that dietary intake of the three major SCFAs, acetate, propionate, and butyrate, protected against HFD-induced obesity, and improved hepatic metabolic conditions via FFAR3 in mice." (PMID 31719611, 2019). "This reduction in FFAR3, due to the intestinal dysbiosis characteristic of obesity, compromises the bacterial production of SCFA and its ability to activate this receptor, thus affecting energy homeostasis and the secretion of intestinal hormones such as PYY and GLP-1." (PMID 41149616, 2025). "The targeted analysis of a subset of jejunum genes in the context of obesity and ME1 expression revealed novel, positive associations of ME1 with two key mediators of intestinal tissue architecture, inflammation, and metabolism, namely TLR9 and FFAR3." (PMID 37047583, 2023). "However, an additional FFAR3-KO mouse model showed that HFD-induced obesity was reduced compared to WT controls, potentially due to increased energy expenditure." (PMID 36678142, 2023). "Indeed, considering the close link between metabolic disturbances and dementia, a deep characterization of the role of FFAR3 is extremely pertinent in order to assess its potential role not only in obesity/T2DM, but also in other related diseases, such as AD." (PMID 36362376, 2022). "Thus, although dysfunctional vagal FFAR3 signaling is not likely a causal factor in obesity, the vagal-FFAR3-dependent anorectic effect of propionate endows it with therapeutic potential." (PMID 34626852, 2021). "As signaling molecules, SCFAs exert anti-obesity effects by activating PPAR-γ in the liver and WAT and G protein-coupled receptors GPR43/FFAR2 and GPR41/FFAR3." (PMID 40867585, 2025).
Obesity (continued). "Similarly, dietary fiber intake can increase the production of SCFAs by gut microbiota, which subsequently stimulates GLP-1 secretion by acting on GPR41/FFAR3 and GPR43/FFAR2 on gut endocrine L cells, thereby improving obesity and IR." (PMID 41321496, 2025). "There was a significant difference in the FFAR3 expression in the duodenum compared to the jejunum in healthy normal weight subjects compared to subjects with obesity with and without T2D." (PMID 38910871, 2024). "Conversely, a mechanistic study showed that butyrate and propionate protect against diet-induced obesity and regulate glucose-dependent insulinotropic peptide (GIP) and GLP-1 secretion independently of FFAR3, indicating a minor role of this FFA receptor in host metabolism." (PMID 36678142, 2023). "This feature evidenced that, strikingly, FFAR3 ablation-facilitated obesity is not present in the Tg2576 AD mouse model." (PMID 36362376, 2022). "Together, these data demonstrate that the need for FFAR3 to prevent HFD-induced obesity and glucose intolerance does not operate in Tg2576 mice, revealing that Tg-FFAR3−/− mice indeed feature enhanced metabolic resilience." (PMID 36362376, 2022). "Thus, considering the importance of FFAs for obesity and T2DM, and the postulated continuum of obesity, T2DM, and AD: (i) is the reversal of AD cognitive dysfunction upon FFAR3 inactivation due to an improvement in energy homeostasis induced by FFAR3 ablation?" (PMID 36362376, 2022).
Hypertension (31 papers, 2019 to 2025). The presence of chronic increased pressure in the systemic arterial system. "In mice, FFAR2 and FFAR3 protect against hypertension through immune-mediated mechanisms." (PMID 41291732, 2025). "Furthermore, in FFAR3 knockout mice an isolated systolic hypertension was found which confirm the role of FFAR3 as a regulator of the blood pressure." (PMID 39024309, 2024). "More specifically, Olfr78 and FFAR3 were found to be expressed in the smooth muscle cells of small resistance blood vessels, and Olfr78 knockout mice, as well as FFAR3 knockout mice, developed hypertension upon antibiotic treatment, which reduced SCFA levels derived from gut microbial fermentation." (PMID 35328722, 2022). "In contrast, a study on Olfr78, an olfactory receptor expressed in the juxtaglomerular apparatus of the kidney and activated by SCFAs, and on FFAR3, demonstrated a clear role for vascular FFAR3 in the regulation of blood pressure/vascular tone and in hypertension." (PMID 35328722, 2022).
colitis (22 papers, 2016 to 2025). Inflammation of the colon. "Another sub-strain, Lactis BL-99, promotes up-regulation of acetate and butyrate receptors, including FFAR2, FFAR3 and GPR109a expression, which negatively correlates with monocytes and macrophages and ameliorates colitis-associated lung injury in mice." (PMID 38110878, 2023). "Moreover, butyrate failed to protect against TNBS-colitis in Hcar2−/− mice, and Ffar2−/− and Ffar3−/− mice were found to be more susceptible to TNBS-colitis." (PMID 38595917, 2024). "Many of the inflammatory cytokines attenuated by FFAR2 and FFAR3, including C5, CCL1, CCL2, GM-CSF, IL-1α, IL-1β, ICAM-1 and TNF, are associated with colitis." (PMID 27667443, 2016). "The potential involvement of monocyte FFAR2 and FFAR3 in human colitis, through the modulation of these cytokines, is therefore conceivable." (PMID 27667443, 2016). "Knockout mice studies implicate the mammalian short-chain fatty acid (SCFA) receptors, FFAR2 and FFAR3– in colitis, arthritis and asthma." (PMID 27667443, 2016). "Further investigations to determine: (i) if FFAR2 or FFAR3 signalling is altered in the monocytes of colitis patients, and (ii) whether this abnormality is involved in disease pathology– may reveal novel insights on colitis and its treatment." (PMID 27667443, 2016). "To elucidate the involvement of the SCFA receptors, FFAR2 and FFAR3, in DSS-induced colitis, we repeated the DSS experiments in dual FFAR2/3 knockout mice." (PMID 39057718, 2024). "In this regard, acute DSS colitis in conventional C57BL/6 mice decreased the expression of Ffar2, Ffar3, and Hcar2, although this result was not confirmed by others." (PMID 38595917, 2024). "These two FAs decreased the inflammatory response in macrophages mediated via FFAR1, FFAR2, FFAR3, and AMPK; attenuated the development of colitis; and were involved in the elimination of C. glabrata from the gut." (PMID 36144406, 2022).
Insulin resistance (13 papers, 2014 to 2025). Increased resistance towards insulin, that is, diminished effectiveness of insulin in reducing blood glucose levels. "It has been reported that FFAR3 contributes to the improvement of insulin resistance by dietary fibers through activation of FFAR3 expressed in the peripheral nerves by SCFAs produced by gut microbes." (PMID 25875123, 2015). "Taken together, we hypothesized that the expression of FFAR2 and FFAR3 was significantly increased in high-fat diet-fed mice in a compensatory manner to improve insulin resistance in visceral fat." (PMID 34074061, 2021). "SCFAs also activate GPR41, also known as FFAR3, in the peripheral nerves, and improve insulin resistance." (PMID 39337693, 2024). "The elevation of FFAR2, FFAR3, GLP-1, and PYY by DOP treatment was another mechanism of insulin resistance improvement in prediabetic mice." (PMID 37372523, 2023). "In addition, the upregulation of FFAR2, FFAR3, GLP-1, and PYY was reported to improve insulin resistance." (PMID 37372523, 2023).
diabetes (11 papers, 2015 to 2024). "FFAR3 has been implicated in energy metabolism, sympathetic function, diabetes, immune function, and interactions with the gut microbiota." (PMID 26260360, 2015). "After RYGB surgery, the expression of FFAR3 was nearly abolished in the alimentary limb in both obese subjects with and without diabetes." (PMID 38910871, 2024). "Among them, the free fatty acid receptor (FFAR) FFAR1 (GPR40), FFAR2 (GPR43), FFAR3 (GPR41), and FFAR4 (GPR120) may bridge the genetic and environmental aspects of diabetes (14, –, 18)." (PMID 37787527, 2023). "Given that ME1, FFAR3, and FFAR2 are all candidate targets for anti-diabetes drugs, further elucidation of the networks/pathways that involve these molecules may prove valuable." (PMID 37047583, 2023).
asthma (9 papers, 2016 to 2025). "FFAR2 and FFAR3 are both associated with metabolic diseases and have become effective targets for the treatment of type 2 diabetes, asthma, cardiovascular diseases, and metabolic syndrome." (PMID 40332278, 2025). "In addition, FFAR3 expression increases on soluble fiber administration with a decrease in macrophages, eosinophils, neutrophils migration, and exhaled nitric oxide synthesis (eNOS) against asthma, so FFAR3 signaling enhances adaptive immune response." (PMID 32521775, 2020).
type 2 diabetes (8 papers, 2014 to 2025). "Reduced methylation in the promoters of proinflammatory genes TLR2 and FFAR3 is correlated with reduced abundance of Faecalibacterium prausnitzii in type 2 diabetes patients." (PMID 28388917, 2017). "The diversity of the gut microbiota and the degree of methylation of the FFAR3 promoter region were significantly lower in the obese and type 2 diabetic patients compared to lean individuals, demonstrating a correlation between a higher body mass index and lower methylation of FFAR3." (PMID 25875123, 2015). "Butyrate could regulate the hypomethylation of the FFAR3 gene and the LINE1 gene, influencing metabolic diseases such as obesity and type 2 diabetes." (PMID 39200098, 2024).
breast carcinoma (7 papers, 2017 to 2026). "FFAR2 and FFAR3 act as tumor suppressors in colon and breast cancer; the loss of FFAR2 promotes colon tumorigenesis." (PMID 35785152, 2022). "This led us to investigate the mechanisms underlying FFAR2- and FFAR3-mediated effects on breast cancer cells, particularly pertaining to metastasis." (PMID 29049318, 2017). "To understand the functions of FFAR2 and FFAR3 in breast cancer metastasis, we evaluated two breast cancer cell lines that have contrasting EMT phenotypes reflected by their EMT score: 1.0 = highly mesenchymal, -1.0 = highly epithelial." (PMID 29049318, 2017). "Since our data suggest that FFAR2 and FFAR3 inhibit EMT, we speculated that expression of these receptors is likely to be reduced in invasive breast cancer tissues." (PMID 29049318, 2017).
allergic disease (4 papers, 2020 to 2025). An immune response that occurs following re-exposure to an innocuous antigen, and that requires the presence of existing antibodies against that antigen. "In addition, FFAR3 pathway stimulated by propionate reduces the lungs’ allergic inflammation and total amount of IgE (antibody associated with allergic reaction) concentration in the serum." (PMID 32521775, 2020). "Further analysis indicated that propionate, mediated through G-protein-coupled receptor 41 (GPR41, also known as FFAR3), plays a crucial role in modulating immune responses and allergic disease progression." (PMID 40431425, 2025). "-Expressed in the mice lungs.-Propionate minimize allergy airway inflammation in mice lungs mediated through FFAR3." (PMID 32521775, 2020). "However, single-cell RNAseq of eosinophilic esophagitis patient T-cell exhibits higher expression of FFAR3 with increased Th2 cytokine (that exacerbate allergies) production." (PMID 32521775, 2020).
hepatocellular carcinoma (4 papers, 2014 to 2020). A malignant tumor that arises from hepatocytes. "In contrast, a role for FFAR3 in the anti-proliferative synergistic effect obtained with propionate and cisplatin on human hepatocellular carcinoma cells has been reported and a recent study reveals that the activation of FFAR3 by SCFAs inhibit bovine epithelial cells proliferation." (PMID 33113952, 2020).
influenza infection (4 papers, 2020 to 2025). "-FFAR3 pathway is associated with airway neutrophil response subjected to influenza infection verified in FFAR3 KO mice." (PMID 32521775, 2020). "Moreover, in influenza infected mice, FFAR3 pathway increases anti-viral immunity activity on dietary fermentable fibers and SCFAs administration." (PMID 32521775, 2020).